TLR5 (toll like receptor 5)
Diseases named in the same sentence as TLR5 in open-access papers (continued):
Sharing a sentence is not in itself a finding about the gene and the disease.
cardiomyopathy (1 paper, 2020). A disease of the heart muscle or myocardium proper. "Collectively, our study found that TLR5 deficiency attenuated DOX-induced cardiomyopathy and improved cardiac function." (PMID 33042267, 2020). "To investigate the role of TLR5 in DOX-induced cardiomyopathy, we initially assessed expression of TLR5 in ventricular samples of mice." (PMID 33042267, 2020). "We then utilized global TLR5 knockout (KO) mice and age-matched wild type (WT) littermates to explore the role of TLR5 protein in DOX-induced cardiomyopathy in a 3-day short-term trial." (PMID 33042267, 2020).
Cerebral ischemia (1 paper, 2021). Restriction of arterial blood supply to the brain associated with insufficient oxygenation to support the metabolic requirements of the tissue. "As an ingredient of Carthami flos, luteolin could downregulate the expression of TLR4, TLR5, NF-κ B, and P-P38MAPK, upregulate the expression of p-ERK, and protect cerebral ischemia in rats." (PMID 33727944, 2021).
Chagas disease (1 paper, 2018). A parasitic infection caused by Trypanosoma cruzi. "Patients with different clinical manifestations of Chagas disease showed similar expression of TLR1, TLR3, TLR4, TLR5, TLR6, TLR7 and TLR9 mRNA." (PMID 30044791, 2018). "On the other hand, patients with different clinical manifestations of Chagas disease showed similar mRNA expression levels of TLR1, TLR3, TLR4, TLR5, TLR6, TLR7 and TLR9." (PMID 30044791, 2018).
Chlamydia infection (1 paper, 2022). "Our study identified TLR5, STAT2 and IFNγ as genes significantly associated with the ability of a koala to resolve a Chlamydia infection." (PMID 35510793, 2022).
chorioamnionitis (1 paper, 2018). A morphologic finding indicating inflammation of the fetal sac membranes. "The aim of this study was to investigate TLR5 expression in placentas with preterm histologic chorioamnionitis (HCA)." (PMID 29371755, 2018). "The role of TLR5 in chorioamnionitis remains unclear: however, TLR5 was reported to have a significantly stronger effect on the induction of interleukin (IL)-6 when compared with other TLRs in amniotic epithelial cells." (PMID 29371755, 2018).
chronic gastritis (1 paper, 2011). Inflammation of the stomach that is chronic in nature. "TLR5 and TLR9 have also been identified in non-inflamed gastric epithelium and in H. pylori-associated chronic gastritis." (PMID 21647408, 2011). "The localization of TLR5 and TLR9 was found to be exclusively basolateral in H. pylori-associated chronic gastritis, suggesting that these two TLRs may not be essential for H. pylori recognition." (PMID 21647408, 2011).
chronic hepatitis C (1 paper, 2021). "In this sense, chronic hepatitis C increases bacterial translocation to the blood, and downregulation of TLR5 may be beneficial for the host in the context of persistent immune stimulation by reducing the immune response and the associated immunopathology." (PMID 33785040, 2021).
colon adenocarcinoma (1 paper, 2010). "One study showed that TLR5 uses gangliosides as co-receptors to bind flagellin leading to increased human beta defensin-2 expression in human colon adenocarcinoma (Caco)-2 cells." (PMID 21203467, 2010).
colorectal adenocarcinoma (1 paper, 2023). The most common type of colorectal carcinoma. "To this end, we stimulated Caco-2 cells, an IEC cell line derived from a human colorectal adenocarcinoma, with the TLR5 agonist flagellin (Fl), with the chemical ER stress inducer thapsigargin (TG), or a combination of both (TGFl)." (PMID 37457727, 2023).
colorectal polyps (1 paper, 2020). "The noteworthy point was that the RQs of TLR2, TLR3, TLR4, and TLR5 were significantly different among histologically different colorectal polyp types compared to samples from normal participants (p-value < 0.001)." (PMID 33255933, 2020). "In fact, TLR3 and TLR5 expression levels were higher in normal individuals, compared to different types of progressive colorectal polyps." (PMID 33255933, 2020). "The aim of our study was to evaluate the expression levels of TLR2, TLR3, TLR4, and TLR5 in intestinal biopsy specimens of patients with different histological colorectal polyp types including HP, SSA, tubular adenoma (TA), and villous/tubulovillous (VP/TVP) cases compared to normal controls." (PMID 33255933, 2020).
colorectal tumor (1 paper, 2020). "In contrast to normal mouse hepatocytes, which are strongly responsive, BNL and Hepa 1–6 HCC tumor cells and CT26 colorectal tumor cells do not respond to TLR5 stimulation with NF-κB activation." (PMID 32027657, 2020).
Cryptosporidium infection (1 paper, 2016). "Signaling TLR3 in combination with TLR5, TLR4 and TLR9 independently influence Cryptosporidium infection outcomes." (PMID 27467505, 2016).
cystic ovary (1 paper, 2023). "In TLR5, the high FDR interpretation suggested an association with cystic ovary incidence in g.545T>C and g.3714C>T, early reproductive disorders in g.3714C>T and g.4626T>C, and maternal calving ease in g.1736C>T." (PMID 38254914, 2023).
dermatitis (1 paper, 2017). An inflammatory process affecting the skin. "It was of interest to evaluate IMQ dermatitis in MOLF mice, since previous studies have identified MOLF genetic variants impacting Toll-like receptor (TLR) signaling, including alleles associated with Tlr5, Irak1bp1, Irak2, Irak2c, and Cyld." (PMID 28279190, 2017).
Dysmenorrhea (1 paper, 2017). Pain during menstruation that interferes with daily activities. "After statistical analysis confirmed that: The gene expression of TLRS (TLRS = TLR1 + TLR2 + TLR3 + TLR4 + TLR5 + TLR6 + TLR7 + TLR8 + TLR9) in severe and moderate dysmenorrhea group was significantly higher than that in minimal dysmenorrhea group in EU and EC (P < 0.05 or P < 0.01)." (PMID 28779087, 2017).
endometriosis (1 paper, 2020). The growth of functional endometrial tissue in anatomic sites outside the uterine body. "In the Endometriosis Group, seven patients had peritoneal Tregs expressing three or more TLR, with TLR5 being the most frequent (in six out of seven patients)." (PMID 32236327, 2020).
endophthalmitis (1 paper, 2014). An infectious process affecting the internal structures of the eye. "Taken together, these results suggest a limited role for flagellin/TLR5 interactions in B. cereus endophthalmitis." (PMID 24959742, 2014). "Since B. cereus is a flagellated bacterium, we hypothesized that B. cereus flagella contributed to the pathogenesis during endophthalmitis by activating the ocular inflammatory response via TLR5." (PMID 24959742, 2014). "This hypothesis was tested by analyzing the immune response against B. cereus flagellin in vitro and in vivo, and by comparing the pathogenesis of B. cereus infection in an experimental model of endophthalmitis in wild type control and TLR5−/− mice." (PMID 24959742, 2014). "Because flagella is a ligand for Toll-like receptor 5 (TLR5), we hypothesized that TLR5 contributed to endophthalmitis pathogenesis." (PMID 24959742, 2014). "Because the motility of B. cereus, and therefore its flagella, are important in the virulence of B. cereus during endophthalmitis, we hypothesized that flagellin/TLR5 interactions also contributed to the pathogenicity of infection." (PMID 24959742, 2014). "Our results demonstrated that B. cereus flagella/TLR5 interactions, if present, did not contribute significantly to endophthalmitis pathogenesis." (PMID 24959742, 2014). "Taken together, these results suggest that B. cereus flagellin/TLR5 interactions in the eye may not be significant enough to greatly impact the overall course of intraocular inflammation during experimental endophthalmitis." (PMID 24959742, 2014).
enteritis (1 paper, 2024). Inflammation of the small intestine. "Enterococcaceae are known as conditional pathogens, because they can cause enteritis in Toll-like receptor 5 (TLR5)-deficient mice." (PMID 38525083, 2024).
fungal keratitis (1 paper, 2014). "TLR5 has been reported to modulate corneal inflammation and the innate antimicrobial response in vitro and is important in ocular inflammation during bacterial and fungal keratitis." (PMID 24959742, 2014).
gastric diseases (1 paper, 2019). "Furthermore, results showed a TLR5 discrepancy between AAG and GC with a predominance of TLR5 rs5744174 in heterozygosis (C/T) in AAG, and in homozygosis (C/C) in GC suggesting a possible role of TLR5 C-allele in increasing the risk for gastric diseases." (PMID 31083432, 2019). "In addition, the interaction between flagellin from other bacteria than H. pylori and TLR5 might have a role in gastric diseases." (PMID 31083432, 2019).
gestational diabetes mellitus (1 paper, 2025). "In models of gestational diabetes mellitus, increased immune markers, including TLR4, TLR5, IL-22, and IL-23, have been detected in the placenta, suggesting a role for TLR4 and TLR5 in the inflammatory processes associated with maternal metabolic disturbances." (PMID 40558558, 2025).
Glucose intolerance (1 paper, 2015). Glucose intolerance (GI) can be defined as dysglycemia that comprises both prediabetes and diabetes. "The glucose intolerance in DIO TLR5−/− mice was more significant than that in DIO C57BL/6 mice and was not attenuated by a switch to the LFD." (PMID 26681840, 2015). "With a 60% higher incremental glucose AUC, the glucose intolerance in DIO TLR5−/− mice was more significant compared to DIO C57BL/6 mice." (PMID 26681840, 2015). "Moreover, glucose intolerance was still significant in LFD-fed TLR5−/− mice than C57BL/6 mice." (PMID 26681840, 2015).
HCMV infection (1 paper, 2020). "During HCMV infection/reactivation, TLR5 plays an atypical role, probably because of the indirect effects of immunomodulation and immunostimulation on HCMV responses." (PMID 33298111, 2020). "TLR3 and TLR5 are also critical factors in the CMV infection pathway." (PMID 33298111, 2020). "HCMV infection stimulates cluster differentiation antigen 14 (CD14), TLR2, TLR4, and TLR5 on the surface to enhance the intracellular expression of the adaptor protein MyD88, and phosphorylation of IκB and NF-κB, thereby increasing the response of macrophages to viral components." (PMID 33298111, 2020).
hepatic diseases (1 paper, 2021). "Toll-like receptor 5 (TLR5)-mediated pathways play critical roles in regulating the hepatic immune response and show hepatoprotective effects in mouse models of hepatic diseases." (PMID 33622404, 2021).
Hepatitis (1 paper, 2021). Inflammation of the liver. "Our studies have shown that the CBLB502-mediated protective effects against Con A-induced hepatitis and male reproductive system damage induced by ionizing radiation mainly rely on the TLR5 pathway, in line with the previous report that radioprotection by CBLB502 is indeed TLR5-dependent." (PMID 33622404, 2021).
jejunal tumors (1 paper, 2024). "A larger proportion of jejunal tumors was observed in SB-NETs with high nucleic TLR5 intensity group compared to low nucleic intensity (10.8% vs. 1.6%, p = 0.043)." (PMID 38709790, 2024).
Kaposi's sarcoma (1 paper, 2023). A malignant neoplasm characterized by a vascular proliferation which usually contains blunt endothelial cells. "One such example is a study between TLR9, HLA class I/II alleles, and a vaccine construct against Kaposi’s sarcoma, while another study on Candida auris vaccine design reported docking between TLR5 and MHC class-II HLA DRB_0101 with scores in a similar range." (PMID 38053576, 2023).
leukemia (1 paper, 2022). A malignant (clonal) hematologic disorder, involving hematopoietic stem cells and characterized by the presence of primitive or atypical myeloid or lymphoid cells in the bone marrow and the blood. "Further studies are necessary to elucidate the role of the TLR1, TLR4, TLR5, TLR6, TLR9, and CD14 polymorphisms in the pathogenesis of leukemia." (PMID 36071076, 2022).
lymphadenitis (1 paper, 2012). Acute or chronic inflammation of one or more lymph nodes. "TLR5 expression correlates with the frequency of lymphadenitis in CGD patients, suggesting a clinically relevant role for TLR5 dysregulation in the course of CGD." (PMID 21808651, 2012).
mycobacterial infection (1 paper, 2024). "It has also been discovered that TLR5 and 13 exhibits markedly elevated expression during an acute mycobacterial infection." (PMID 39483482, 2024). "Following mycobacterium infection, the zebrafish exhibits upregulation of the TLR1, TLR5, TLR18, TLR20, and TLR22 genes." (PMID 39483482, 2024).
mycoplasmal pneumonia (1 paper, 2022). "NOD2 and TLR5 SNPs were associated with pleuritis, whereas NLRP3 SNPs were associated with an index of mycoplasmal pneumonia." (PMID 36428390, 2022).
myeloma (1 paper, 2013). "Expression of mRNA for TLR1, TLR3, TLR4, TLR5, TLR7, TLR8, and TLR9 was found in all myeloma cell, but levels of mRNA expression differed amongst different cell lines." (PMID 23593278, 2013).
neuropathic pain (1 paper, 2021). Chronic pain caused by damage to nerve fibers. "In summary, our current findings suggest that nerve decompression improves CCI-induced mechanical hyperalgesia that might be through the cross-talk of TLR5 and MOR in a PKCα-dependent manner, which opens a novel opportunity for the development of analgesic therapeutics in neuropathic pain." (PMID 33673008, 2021).
ocular infection (1 paper, 2019). "TLR5-knockout mice are more susceptible to P. aeruginosa ocular infection, indicating the role of TLR5 in the forming of protective mucosal surfaces against the infection by flagellated bacteria." (PMID 30944709, 2019).
ocular melanoma (1 paper, 2016). A melanoma that arises from the structures of the eye or ocular adnexa. "The goal of this study was to explore the potential of entolimod as an immunotherapeutic agent against hepatic metastasis of UM using the TLR5-positive B16LS9 mouse model of ocular melanoma." (PMID 26655090, 2016). "In summary, this study demonstrates that the TLR5 agonist entolimod potently suppresses hepatic metastasis in the mouse B16LS9 ocular melanoma model when administered before or after tumor cell inoculation." (PMID 26655090, 2016).
otitis media (1 paper, 2021). Inflammation of the anatomical structures of the middle ear, which is most often caused by an infectious process. "These authors reported that, among non-otitis media, COM, and chronic suppurative otitis-media (CSOM) groups, mRNA and protein levels of TLR5 were significantly reduced in the CSOM group, but were not different between non-otitis media and COM groups." (PMID 34360632, 2021).
pancreatic cancer (1 paper, 2021). "Little is known about the role of TLR5 in pancreatic cancer." (PMID 34884547, 2021). "However, it has recently been shown that ligands within the gut microbiome of pancreatic cancer patients are recognized by TLR5, which, upon interaction with TLR2, activates a signaling cascade that leads to the cancer growth enhancement and to the suppression of innate and adaptive immune response." (PMID 34884547, 2021).
pancreatic ductal adenocarcinoma (1 paper, 2019). An infiltrating adenocarcinoma that arises from the epithelial cells of the pancreas. "Cox regression survival analysis of patients with pancreatic ductal adenocarcinoma related to clinicopathological characteristics and TLR1, TLR3, TLR5, TLR7, and TLR9 immunoexpression." (PMID 31314777, 2019).
papilloma (1 paper, 2015). A benign epithelial neoplasm that projects above the surrounding epithelial surface and consists of villous or arborescent outgrowths of fibrovascular stroma. "Leukocytic TLR-5 signalling mediates upregulation of the alarmin HMGB1 (High Mobility Group Box 1) in wound-induced papillomas." (PMID 25575023, 2015). "We demonstrate that TLR-5 ablation in BM-derived leukocytes reduced tumour incidence in mice and injection of the TLR-5 ligand flagellin induced papillomas in a TLR-5-dependent manner." (PMID 25575023, 2015). "TLR-5−/− BM reconstitution did not reduce the final number of papillomas that formed but decreased tumour size considerably." (PMID 25575023, 2015).
pertussis (1 paper, 2019). A contagious bacterial respiratory infection caused by Bordetella pertussis. "Our results suggest that TLR5 agonists could significantly increase the performance of the current acellular pertussis vaccine." (PMID 31889098, 2019).
Pleuritis (1 paper, 2022). Inflammation of the pleura. "The nonsynonymous polymorphism TLR5-1205, related to flagellin recognition, might be involved in the eradication of App in natural infection and might have influenced the pleuritis that we observed here." (PMID 36428390, 2022).
polyp (1 paper, 2020). A usually exophytic mass attached to the underlying tissue by a broad base or a thin stalk. "In contrast, TLR3 and TLR5 were downregulated in all patient polyp types compared with normal tissue samples." (PMID 33255933, 2020). "In addition, lower expression rates were observed for TLR3 and TLR5 in all polyp groups in contrast to normal individuals (p-value < 0.001)." (PMID 33255933, 2020).
prostate tumors (1 paper, 2020). "In mice, Mobilan injection into prostate tumors resulted in autocrine TLR5 signaling, immune system activation, and suppression of tumor growth and metastasis." (PMID 32292576, 2020).
psychosis (1 paper, 2020). "Recent research studies described that the correct expression of TLR5 during neonatal period influences the long-term gut microbiota composition, and the alteration of microbiota was related to psychosis in at least a subgroup of patients." (PMID 32854231, 2020). "The results of our study highlight the role that TLR5 and TLR8 might play in the pathophysiology of psychosis." (PMID 32854231, 2020). "We highlight the role that TLR5 and TLR8 might have in the pathophysiology of psychosis." (PMID 32854231, 2020).
Pv (1 paper, 2017). "The genotypes C/T (TLR5 R392StopCodon) and T/T (TLR9 -1486C/T) appear to be risk factors for Pv-infection (TLR5: C/C vs. C/T OR = 2.1 [95% CI: 1.1–4.5, p = 0.031]; TLR9: C/C vs. T/T OR = 1.9, [95% CI: 1.2–3.2, p = 0.01]; TLR9: C/C vs. C/T+T/T OR = 1.6, [95% CI: 1.1–2.5, p = 0.024])." (PMID 28850598, 2017).
radiation sickness (1 paper, 2023). "An essential role of neutrophil was recently reported in a TLR5 mitigation of a lethal acute radiation sickness." (PMID 37953266, 2023).
rheumatic diseases (1 paper, 2015). "We identified a total of eight differentially expressed genes (TNFSF10, CX3CR1, LY96, TLR5, TXN, TIA1, PRKCH, PRF1), each associated with at least 3 of the 4 studied rheumatic diseases." (PMID 26352601, 2015). "By jointly analyzing 6 published microarray gene expression datasets about RA, SLE, OA and AS, we identified eight genes (TNFSF10, CX3CR1, LY96, TLR5, TXN, TIA1, PRKCH, PRF1) presenting general importance to rheumatic diseases." (PMID 26352601, 2015).
salmonellosis (1 paper, 2012). Infections with bacteria of the genus salmonella. "Flagella also exhibit adjuvant properties acting as a TLR5 agonist, which render this structure a protective antigen against salmonellosis." (PMID 23056473, 2012).
Senile plaques (1 paper, 2024). Senile plaques are extracellular deposits of amyloid in the gray matter of the brain. "Additionally, other studies have demonstrated the increased expression of TLR2, TLR4, TLR5, TLR7, TLR9, and the co-receptor CD14 in microglial cells surrounding senile plaques in the brain tissues of patients with AD and AD mouse models." (PMID 38360834, 2024).
skin infection (1 paper, 2018). An inflammatory process affecting the skin, caused by bacteria, viruses, parasites, or fungi. "This study suggests that flagellin is a key PAMP of P. aeruginosa during skin infection and that TLR5 is the main pattern recognition receptor involved in P. aeruginosa recognition by keratinocytes." (PMID 30070169, 2018).